MTOR (mechanistic target of rapamycin kinase)
Diseases named in the same sentence as MTOR in open-access papers (continued):
Sharing a sentence is not in itself a finding about the gene and the disease.
non-small cell lung carcinoma (continued). "However, COLI in non-small cell lung cancer (NSCLC) induced mTOR activation through an AKT-independent pathway, leading to EGFR-tyrosine kinase inhibitor resistance." (PMID 31521169, 2019). "Similarly, the PI3K/AKT/mTOR signaling pathway is commonly deregulated in human malignancy including non-small cell lung cancer (NSCLC)." (PMID 29587825, 2018). "In human non-small cell lung cancer, PD-L1 is also induced by mTOR activation." (PMID 29728568, 2018). "Previous studies revealed the induction of autophagy by PLB in different cancer cell lines via the negative PI3K/Akt/mTOR axis modulation As per Wang's previous data autophagy was induced through inhibition of the PI3K/Akt/mTOR pathway in non-small-cell lung cancer cells." (PMID 29311925, 2017). "In this study, we evaluated the therapeutic efficacy of AZD6244 alone or with BEZ235, an orally available potent inhibitor of phosphatidylinositol 3–kinase (PI3K) and mammalian target of rapamycin (mTOR), in gefitinib-resistant non-small cell lung carcinoma (NSCLC) models." (PMID 24939055, 2014). "On the other hand, in the study of Faber and colleagues, inhibition of PI3K/mTOR signalling in non-small cell lung cancers with activating mutations of EGFR did not induce apoptosis, in contrast to HER2-amplified breast tumours in which sensitivity was seen." (PMID 21649578, 2011). "In contrast to the HER2-amplified breast tumours, inhibition of PI3K/mTOR signalling non-small cell lung cancers with activating mutations of EGFR did not induce apoptosis." (PMID 21649578, 2011). "CK1α has dual effects on autophagic regulation: on the one hand, the inhibition of CK1α can activate the mTOR signalling pathway to inhibit autophagy; on the other hand, the overexpression of CK1α can increase autophagic flux in non-small cell lung cancer (NSCLC) cells." (PMID 41234362, 2025). "Additionally, miRNAs − 101-3p reversely modulates the activity of mTOR, suggesting that miRNAs − 101-3p could be essential for non-small cell lung cancer radiosensitivity." (PMID 38965615, 2024). "Moreover, the flavonoid wogonoside isolated from the root of Scutellaria baicalensis Georgi induced apoptosis accompanied by mitochondrial dysfunction, which was mediated by decreased ATP levels activating AMPK/mTOR signaling in human non-small-cell lung cancer A549 cells." (PMID 35840761, 2022). "Similarly, PEBP4 knockdown can activate extracellular signal-regulated kinase 1/2 (ERK1/2) pathway, thereby inhibiting proliferation and migration in glioma cells, whereas its overexpression can potentiate tumor growth by stimulating PI3K/Akt/mTOR pathway in non-small cell lung cancer (NSCLC)." (PMID 36120358, 2022). "Hyperphosphorylation of this protein via AKT/mTOR/p70S6K pathway was relevant to the progression of non-small cell lung carcinoma (NSCLC)." (PMID 34208799, 2021). "Therefore, morphine binds specifically to MOR and subsequently activates the Src/PI3K/AKT/mTOR pathway through a cascade effect at low concentrations, thus promoting the proliferation, migration, and invasion of H460 non-small cell lung cancer cells and inhibiting apoptosis in vitro." (PMID 34823532, 2021). "Additionally, PRR11 activated the Akt/mTOR autophagy signaling pathway to facilitate tumorigenesis in non-small cell lung cancer, suggesting that this gene may affect cancer cells through different signal transduction pathways." (PMID 34488538, 2021). "Dong synthesized a novel hybrid of 3-benzyl coumarin deca-B-ring derivative and nitric oxide donor benzenesulfonyl furan glycans, and confirmed that this hybrid could inhibit the expression of mTOR and the phosphorylation of mTOR and Akt in non-small-cell lung cancer cells." (PMID 33344242, 2020).
non-small cell lung carcinoma (continued). "In summary, apart from its protective effect on cisplatin-induced nephrotoxicity, Ori enhanced cisplatin sensitivity via its pro-apoptotic activity mediated by AMPK/Akt/mTOR-dependent autophagosome activation, which may be a potential therapeutic target for non-small cell lung cancer." (PMID 31475112, 2019). "Interestingly, the level of immune checkpoint ligands such as programmed death ligand 1 (PD-L1) appears to be regulated by the PI3K-Akt-mTOR pathway: inhibition of PI3K, Akt or mTOR decreased expression of PD-L1 in a non-small cell lung cancer model in vitro and in vivo." (PMID 31093356, 2018). "Furthermore, preclinical data in non-small cell lung cancer (NSCLC) reported that mTOR-dependent, statin-induced inhibition of Akt phosphorylation and nuclear translocation sensitizes cells to etoposide and other cytostatic drugs which supports our clinical findings." (PMID 26735301, 2016). "Since in non-small cell lung cancer cell lines the BGT226-dependent modulation of PI3K/Akt/mTOR signal axis has been demonstrated, we determined whether this drug also affected downstream signal transduction factors that promote PI3K/Akt/mTOR-mediated cell survival." (PMID 26003166, 2015). "In non-small cell lung cancer cells, the combination of sertraline and erlotinib enhanced autophagy activation and tumor cell death through the mutual regulation of the AMPK/mTOR/S6K pathways." (PMID 40502851, 2025). "In non-small cell lung cancer, MYH9 activates the mTOR signaling pathway, enhancing stemness features." (PMID 39988672, 2025). "In non-small-cell lung cancer (NSCLC) models, the overexpression of Sirtuin 6 (SIRT6) downregulates p-PI3K, p-AKT, and p-mTOR levels, significantly inhibiting the expression of the proliferation marker Ki-67." (PMID 40725100, 2025). "Previous studies by our group have shown that FGFC1 selectively inhibits erlotinib-resistant non-small cell lung cancer by inhibiting the NF-κB and PI3K/Akt/mTOR pathway-mediated ROS elevation." (PMID 40894196, 2025). "Conversely, at not dissimilar levels (25-30%), deuterated water impaired tumor cell growth in in a mouse human pancreatic tumor model and in non-small cell lung cancer cell lines (through microtubule depolymerization and inhibition of PI3K/Akt/mTOR signaling)." (PMID 40356903, 2025). "In non-small cell lung cancer, too, CD164 activates mTOR or ABC transporter signaling pathways to promote tumor initiation and chemoresistance." (PMID 40692786, 2025). "MARK kinases, members of the AMPK-related kinase family, potentiate the AMPKα1/mTOR/HIF-1α signaling axis, contributing to the Warburg effect and cell proliferation in non-small cell lung cancer." (PMID 39575238, 2024). "In human non-small-cell lung cancer, MOR overexpression promotes Akt and mTOR activation, tumor growth, and metastasis." (PMID 38920719, 2024). "In non-small cell lung cancer (NSCLC), ICA suppresses tumor growth by inhibiting the PI3K/Akt/mTOR pathway." (PMID 39759453, 2024). "In human non-small cell lung carcinoma (NSCLC) A549 cell line, curcumin-induced apoptosis and reduced migration and invasion through miR-206 upregulation and suppression of the PI3K/AKT/mTOR signaling pathway." (PMID 38201989, 2024). "Non-small cell lung cancer (NSCLC) is a frequent type of solid tumor in both genders, where aberrant regulation of the mTOR pathway contributes to the development of oncogenesis, apoptosis resistance, angiogenesis, cancer progression, and metastasis." (PMID 37566093, 2023). "EGF was shown to induce the expression of CXC Chemokine Receptor 4 (CXCR4) and promote migration in normoxic non-small cell lung cancer (NSCLC) cells via HIF-1α and the PI3K/AKT and mTOR pathways." (PMID 35158804, 2022).
non-small cell lung carcinoma (continued). "Overexpression of FGFR1 in resistant to gefitinib (EGFR inhibitor) NSCLC (non-small-cell lung cancer) cells led to increased activation of AKT and mTOR, whereas FGFR1 inhibition decreased phosphorylation of both kinases and re-sensitized cells to gefitinib." (PMID 34830951, 2021). "In other study, exogenous FAM83D overexpression promoted, while FAM83D silencing inhibited non-small-cell lung cancer (NSCLC) cell proliferation, epithelial-mesenchymal transition, and invasion through regulating the AKT/mTOR pathway." (PMID 33747255, 2021). "It was demonstrated the high levels of CB2 expression in patients with advanced non-small-cell lung cancer and, conversely, the low expression of CB2 suppresses the Akt/mTOR pathway." (PMID 34576321, 2021). "miRNA-21 combined with cisplatin inhibits glycolysis and induces cell death through the PI3K/AKT/mTOR/HIF-1α pathway, improves the cytotoxicity of cisplatin, and provides a theoretical basis for the treatment of cisplatin-resistant non-small cell lung cancer." (PMID 34046349, 2021). "Downregulation of Krüppel-like factor 5 can inhibit hypoxia-induced cisplatin resistance in non-small-cell lung cancer, and its mechanism is via the inhibition of HIF-1α-dependent glycolysis through the inactivation of the PI3K/AKT/mTOR pathway." (PMID 34540667, 2021). "In non-small cell lung cancer, the LKB1/AMPK axis suppresses mTOR activity and promotes cell growth inhibition." (PMID 34451892, 2021). "It was reported that miR-145-3p is down-regulated in non-small cell lung cancer, and inhibited cell migration and invasion by targeting PDK1 via the mTOR signaling pathway." (PMID 34350110, 2021). "In non-small-cell lung carcinoma (NSCLC), aberrant activation of mammalian target of rapamycin (mTOR) contributes to tumorigenesis and cancer progression." (PMID 34178653, 2021). "In the KEGG analysis, hub driving genes were significantly enriched in the well-known cancer-related pathways, such as mTOR, MAPK, ErbB signaling pathways, cell cycle, and non-small cell lung cancer." (PMID 32196072, 2020). "The upregulation of these enzymes on MDSCs is induced by TGF-β-mTOR-HIF-1 signaling and has been reported in peripheral blood and tumor tissues from non-small cell lung cancer (NSCLC) patients." (PMID 32325683, 2020). "Compound K inhibited proliferation, augmented autophagy, and apoptosis of non-small cell lung cancer (NSCLC) (A549 and H1975) cells through the mammalian target of rapamycin (mTOR)/AMPK and JNK signaling pathways." (PMID 32664389, 2020). "For examples, DANCR exerted tumor promoter in non-small cell lung cancer by directly targetting miR-758-3p; and DANCR controlled mTOR expression to modulate tumor progression via sponging miR-496." (PMID 30910842, 2019). "miR-7-5p is more of a tumor suppressor that represses oncogenic proteins such as EGFR, IGF1R, IRS-1, IRS-2, RAF1, PIK3CD, mTOR, and PI3K, in various cancers including PDAC, liver, breast, non-small cell lung carcinoma (NSCLC), colorectal (CRC) and ovarian." (PMID 31510100, 2019). "In non-small cell lung cancer, IGF-1 treatment of erlotinib-inhibited cells increased IGF1R/EGFR heterodimerization, leading to mTOR-mediated synthesis of EGFR and survivin, which counteracted the antiproliferative effects of Erlotinib." (PMID 30729097, 2019). "It has been demonstrated that Sal suppresses AKT1 activity through ATF4- DDIT3/CHOP- TRIB3- AKT1 axis in human non-small cell lung cancer (NSCLC) cells after activation of ER stress response, resulting in mTOR inhibition and autophagy consequently." (PMID 29433536, 2018).
non-small cell lung carcinoma (continued). "In non-small-cell lung cancer (NSCLC) combined HDAC and mTOR inhibition resulted in a synergistic decrease of migration and invasion in vitro and diminished metastasis rates in vivo." (PMID 29299126, 2017). "Here, we analyzed in two different human non-small cell lung cancer xenograft models the effects of a single fraction of IR on the long term expression and activation of the AMPK and the Akt-mTOR pathways, as well as their upstream regulator ATM." (PMID 22607554, 2012). "More recently, we showed that both EGF and hypoxia can induce CXCR4 expression in non-small cell lung cancer (NSCLC) cells via the VHL/HIF-1α axis and this process is regulated by both the PI3-kinase/PTEN/AKT/mTor pathway and hypoxia." (PMID 17083723, 2006). "In non-small-cell lung cancer (NSCLC), resistance to agents such as paclitaxel (Taxol®) and cisplatin often involves epithelial–mesenchymal transition (EMT), activation of PI3K/AKT/mTOR and MAPK pathways, and alterations in microtubule-regulating proteins." (PMID 41011117, 2025). "Another study showed that CSNK1A1 inhibits the growth of non-small cell lung cancer by inducing autophagy via the AKT/FOXO3a/ATG7 pathway without affecting mTOR activity." (PMID 41213929, 2025). "Similarly, in human non-small cell lung cancer A549 cells, vitexin induces apoptosis by inhibiting the PI3K/Akt/mTOR pathway, which supports the findings of this study." (PMID 40283879, 2025). "In non-small cell lung cancer (NSCLC), MALAT1 is overexpressed and enhances tumor cell proliferation, migration, and invasion by activating signaling pathways such as ERK/MAPK and Akt/mTOR, thereby promoting bone metastasis." (PMID 40872531, 2025). "As such, it is a simple aromatic aldehyde, and it has been shown in vitro to suppress multiple oncogenic signaling pathways, including PI3K/Akt/mTOR, NF-κB, STAT3, and ERK, by disrupting the 14-3-3-mediated protein interactions in pancreatic (BxPC-3) and non-small-cell lung cancer (A549) cell lines." (PMID 40940853, 2025). "Among non-small cell lung cancers (NSCLC), 90% of adenocarcinomas, 40% of squamous cell carcinomas, and 60% of large cell carcinomas are characterized by increased activity of PI3K/Akt/mTOR axis." (PMID 38515456, 2024). "Additionally, 2DG enhances the sensitivity of non-small cell lung cancer to crizotinib by inhibiting both HK2-mediated glycolysis and the AKT/mTOR signaling pathway." (PMID 39609317, 2024). "It was investigated in non-small-cell lung cancer (NSCLC) cells with various EGFR statuses whether co-inhibiting PI3K and mTOR would improve the therapeutic outcomes." (PMID 37046703, 2023). "Dinatin is also known as hispidulin, and it can induce ROS-mediated apoptosis of human non-small cell lung cancer cells by activating the ER stress pathway and ER stress-induced apoptosis of human liver cancer cells by activating the AMPK/mTOR signaling pathway." (PMID 35707465, 2022). "A clinical trial of restapimycin (IPI-504) and everolimus (an mTOR inhibitor) has been conducted in patients with KRAS-mutant non-small cell lung cancer, however study results are not yet public (NCT01427946)." (PMID 34502310, 2021). "On the basis of previous findings, they screened the entire genome (16,019 genes) in shRNA-infected KRAS-mutant non-small-cell lung cancer (NSCLC) H23 cells, trying to identify triple combination therapies using ARS-1620, mTOR inhibitors and the IGF1R inhibitor linsitinib." (PMID 34257597, 2021). "Curcumin could inhibit the cell proliferation and induce apoptosis of non-small cell lung cancer (NSCLC) cells via up-regulating the expression of miRNA-206/miRNA-192-5p and suppressing the PI3K/AKT/mTOR signaling pathway." (PMID 33912467, 2021).
non-small cell lung carcinoma (continued). "Further study has indicated that yuanhuacine could also be anticancer bioactive against H1993 human non-small cell lung cancer (NSCLC) cells both in vitro and in vivo by modulation of the AMPK/mTOR signaling pathway." (PMID 34771007, 2021). "This potential role of mTOR activation in initial cell transformation as opposed to progression was also proposed in non small cell lung cancer and intrahepatic cholangiocarcinomas, where mTOR activation was found in well-differentiated tumor cells." (PMID 27096957, 2016). "These pathways included biological proliferation or differentiation related pathways relevant in cancer such as ErbB, mTOR, WNT, TGFβ, MAPK or PI3K/AKT signaling pathways, involved in melanogenesis, colorectal, prostate, endometrial or non-small cell lung cancer." (PMID 26334097, 2015). "In epidermal growth factor receptor (EGFR) mutant non-small cell lung cancer cells, MCL-1 downregulation by a PI3K/mTOR kinase inhibitor in combination with BIM upregulation (a pro-apoptotic member of the bcl-2 family) by a MEK inhibitor has been shown to be critical for the induction of apoptosis." (PMID 22808163, 2012). "Similarly, in non-small cell lung cancer, OTUB2 could bind to U2AF2 and deubiquitinate it, making U2AF2 more stable, promoting the Warburg effect of tumors through the AKT/mTOR signaling pathway." (PMID 38819228, 2024). "Likewise, it has been found that the newer targeted therapy, including inhibitors of EGFR, ALK, PI3K/AKT/mTOR, RAS-MAPK, RET, MET, BRAF, and NTRK/ROS1, as well as PD1 and CTLA4 molecules, for non-small cell lung cancer (NSCLC) have far better treatment responses than the standard therapies." (PMID 39157206, 2024). "Importantly, in non-small-cell lung cancer specimens, the 5p13 amplification correlated with an increased mTOR expression and phosphorylation of the TOR substrate p70 S6 kinase, supporting the hypothesis that GOLPH3 might control mTOR activity in mammalian cells." (PMID 40136688, 2025). "PTEN regulates autophagy in PTEN/AKT/FOXO3a/ATG7 axis in non-small-cell lung cancer (NSCLC) cells, independent of mTOR and Beclin-1." (PMID 33344463, 2020).